CTSL (cathepsin L)
Description:
Thiol protease important for the overall degradation of proteins in lysosomes (Probable). Plays a critical for normal cellular functions such as general protein turnover, antigen processing and bone remodeling. Involved in the solubilization of cross-linked TG/thyroglobulin and in the subsequent release of thyroid hormone thyroxine (T4) by limited proteolysis of TG/thyroglobulin in the thyroid follicle lumen (By similarity). In neuroendocrine chromaffin cells secretory vesicles, catalyzes the prohormone proenkephalin processing to the active enkephalin peptide neurotransmitter (By similarity). In thymus, regulates CD4(+) T cell positive selection by generating the major histocompatibility complex class II (MHCII) bound peptide ligands presented by cortical thymic epithelial cells. Also mediates invariant chain processing in cortical thymic epithelial cells (By similarity). Major elastin-degrading enzyme at neutral pH. Accumulates as a mature and active enzyme in the extracellular space of antigen presenting cells (APCs) to regulate degradation of the extracellular matrix in the course of inflammation (By similarity). Secreted form generates endostatin from COL18A1. Critical for cardiac morphology and function. Plays an important role in hair follicle morphogenesis and cycling, as well as epidermal differentiation (By similarity). Required for maximal stimulation of steroidogenesis by TIMP1 (By similarity). (Microbial infection) In cells lacking TMPRSS2 expression, facilitates human coronaviruses SARS-CoV and SARS-CoV-2 infections via a slow acid-activated route with the proteolysis of coronavirus spike (S) glycoproteins in lysosome for entry into host cell. Proteolysis within lysosomes is sufficient to activate membrane fusion by coronaviruses SARS-CoV and EMC (HCoV-EMC) S as well as Zaire ebolavirus glycoproteins. [Isoform 2]: Functions in the regulation of cell cycle progression through proteolytic processing of the CUX1 transcription factor. Translation initiation at downstream start sites allows the synthesis of isoforms that are devoid of a signal peptide and localize to the nucleus where they cleave the CUX1 transcription factor and modify its DNA binding properties.
Synonyms: MEP; CTSL1; FLJ31037; CATL
Tractability: Small molecule: a structure with a bound ligand is known; a high-quality ligand is known; it belongs to a druggable protein family. Antibody: its Gene Ontology location is reachable by antibodies, with high confidence; UniProt places it where antibodies can reach, with medium confidence; UniProt predicts a signal peptide or a membrane-spanning region. PROTAC: ubiquitination databases record sites on it; its protein half-life has been measured; a small molecule that binds it is known.
Target class: Cysteine protease; Cysteine protease CA clan; Enzyme; Protease; Cysteine protease C1A family
Chemical probes: ML036, PD134560, RELACATIB (high quality), SID 26681509
Gene: Protein-coding gene on chromosome 9 (87,724,051 to 87,731,469, forward strand). Ensembl gene ENSG00000135047.
Subcellular location: Lysosome; Apical cell membrane; Cytoplasmic vesicle, secretory vesicle, chromaffin granule; Secreted, extracellular space; Secreted; Nucleus (Isoform 2)
Subcellular location (Human Protein Atlas): Golgi apparatus; Vesicles
Pathways (Reactome):
Extracellular matrix organization: Assembly of collagen fibrils and other multimeric structures; Collagen degradation; Degradation of the extracellular matrix
Immune System: Endosomal/Vacuolar pathway; MHC class II antigen presentation; Trafficking and processing of endosomal TLR
Cell-Cell communication: Degradation of CDH1; SRC activates STAT3 in a quantitative manner, through Cadherin-11 (CDH11), RAC1 and gp130 (IL6ST)
Disease: Attachment and Entry
Gene expression (Transcription): RUNX1 regulates transcription of genes involved in differentiation of keratinocytes
Metabolism: HS-GAG degradation
Gene Ontology:
Molecular function: collagen binding; cysteine-type endopeptidase activity; cysteine-type peptidase activity; fibronectin binding; histone binding; protein binding; proteoglycan binding; serpin family protein binding
Biological process: adaptive immune response; cellular response to thyroid hormone stimulus; collagen catabolic process; fusion of virus membrane with host endosome membrane; fusion of virus membrane with host plasma membrane; protein autoprocessing; protein catabolic process; proteolysis; receptor-mediated endocytosis of virus by host cell; symbiont entry into host cell; zymogen activation; antigen processing and presentation; antigen processing and presentation of exogenous peptide antigen via MHC class II; antigen processing and presentation of peptide antigen; CD4-positive, alpha-beta T cell lineage commitment; elastin catabolic process; enkephalin processing; macrophage apoptotic process
Cellular component: extracellular exosome; extracellular matrix; extracellular region; lysosome; multivesicular body; nucleus; plasma membrane; apical plasma membrane; chromaffin granule; endocytic vesicle lumen; endolysosome lumen; lysosomal lumen
Genetic constraint (gnomAD): Loss-of-function variants: 23 observed, 34.95 expected, observed/expected ratio (o/e) 0.66, 90% interval 0.47 to 0.93. The upper end of that interval is the gene's LOEUF score, 0.93, which puts it in group 3 of 6, group 1 being the genes least tolerant of losing a copy. Missense variants: 342 observed, 408.54 expected, observed/expected ratio (o/e) 0.84, 90% interval 0.76 to 0.92. Synonymous variants: 123 observed, 139.37 expected, observed/expected ratio (o/e) 0.88, 90% interval 0.76 to 1.02.
Homologues: Orthologues: chimpanzee CTSL (100% identical), macaque CTSL (96% identical), pig CTSL (77% identical), zebrafish ctsl.1 (53% identical), zebrafish ctss1 (44% identical), zebrafish zgc:110239 (40% identical), Drosophila melanogaster CtsL4 (37% identical), Drosophila melanogaster CtsK1 (37% identical), tropical clawed frog ctsl (37% identical), Drosophila melanogaster CtsF (35% identical), Drosophila melanogaster CtsL3 (35% identical), Drosophila melanogaster CtsL2 (35% identical), and 30 more. Paralogues in human: CTSV (77% identical), CTSK (50% identical), CTSS (48% identical), CTSH (38% identical), CTSF (34% identical), CTSW (29% identical), CTSO (28% identical), CTSC (28% identical), CTSZ (23% identical), CTSB (23% identical), TINAGL1 (21% identical), TINAG (20% identical).
Diseases named in the same sentence as CTSL in open-access papers:
CTSL is named in the same sentence as 258 diseases in open-access papers, as found by Europe PMC text mining. Sharing a sentence is not in itself a finding about the gene and the disease. The quoted sentences say what the papers report.
COVID-19 (92 papers, 2020 to 2026). A disease caused by infection with severe acute respiratory syndrome coronavirus 2. "Our findings unveil the role of high glucose in promoting CTSL maturation and translocation from the endoplasmic reticulum to the lysosome, potentially exacerbating diabetic complications and contributing to COVID-19 susceptibility among diabetic individuals." (PMID 39150053, 2024). "This confirmed that people with diabetes had more severe COVID-19 and that higher levels of cathepsin L are linked to more severe disease." (PMID 39150053, 2024). "Recent studies have indicated that female cancer patients have an increased infection risk and develop more severe forms of COVID-19, and overexpression of CTSL pivotal for COVID-19 infection is a marker of invasion and metastasis in ovarian cancer." (PMID 33968933, 2021). "A recent report found that COVID-19 patients had elevated circulating levels of CTSL, and that the levels of CTSL were associated with disease duration and severity." (PMID 35053020, 2021). "In COVID-19 patients, transcriptomic analysis of peripheral blood mononuclear cells showed a significant increase in the expression of cathepsin L and B genes associated with the apoptotic pathway." (PMID 33137165, 2020). "Interestingly, we did observe that certain COVID-19-associated genes, including CTSL and NRP-1, were significantly downregulated specifically in the AD cells following infection." (PMID 38098019, 2023). "In the present study, we assessed the expression levels of viral entry receptors such as CTSL in HNSC cancer tissues since malignant pathology may influence COVID-19 susceptibility and sickness." (PMID 37292206, 2023). "Mainly, in the different articles, the following types of proteases were analyzed, and it was observed that a high level of furin, cathepsin B, cathepsin L, and cathepsin G may increase the risk of COVID-19 complications." (PMID 35224542, 2022). "However, CTSL tended to be comparable in CD4 + T cells from COVID-19 pneumonia patients, suggesting the particularity of CTSL in T cells infected with the virus that causes COVID-19." (PMID 34497809, 2021). "Among the proteases, TMPRSS2, Cathepsin L, and Furin mRNA were upregulated in the kidney of DHT-treated female mice suggesting an increased susceptibility to SARS-CoV-2 renal infection in women with PCOS." (PMID 33922918, 2021). "It has also been proposed that patients with periodontitis show increased levels of different proteases (furin, cathepsin B, cathepsin L, cathepsin G), which may favour a more severe COVID-19, since they have been shown to increase the risk of complications in COVID-19 patients." (PMID 37133697, 2023). "The activity of cathepsin S and cathepsin L were greater in the urine of the COVID-19-positive participant group compared to the COVID-19-negative participant group." (PMID 39861814, 2024). "We also found a statistically significant increase in CTSL, AngII and TNFα values in vaccinated individuals compared to both healthy controls and COVID-19 patients." (PMID 38137381, 2023). "Analyzing serum CTSL levels, we found that the vaccinated group had the highest values compared to the other groups, and in some patients with moderate COVID-19, CTSL levels were lower compared to severe COVID-19." (PMID 38137381, 2023). "Elevated in the serum of COVID-19 patients, CTSL mediates viral entry by participating in the cleavage of the viral S protein." (PMID 35021853, 2022). "All these data indicate a potential role of CTSL in COVID-19 pathogenesis in normal and cancerous tissues of the lungs." (PMID 35414771, 2022). "Further analysis of the correlation with invasion genes showed that the entry factor genes (BSG, FURIN, and CTSL) were positively correlated with the ratio of early EndMT in COVID-19, and CTSL was positively correlated with the ratio of early EndMT in IPF." (PMID 36248845, 2022).
COVID-19 (continued). "We investigated the inhibitory properties of the synthesised complexes towards two enzymes involved in the development of COVID-19, namely cathepsin L and SARS-CoV-2 PLPro." (PMID 35943189, 2022). "Cysteine proteases comprise an important class of drug targets, especially for infectious diseases such as Chagas disease (cruzain) and COVID-19 (3CL protease, cathepsin L)." (PMID 35860632, 2022). "As a result, human cathepsin L comprises an additional cellular target for the development of anti–COVID-19 agents." (PMID 35860632, 2022). "Here, for the first time, we report the crucial role of cathepsin L (CTSL) in patients with COVID-19." (PMID 33774649, 2021). "Cysteine protease CTSL expression is upregulated during chronic inflammation and is involved in processing the COVID-19 spike protein." (PMID 34445093, 2021). "CTSL and CTSL/CTSB increased in COVID-19 patients than in healthy individuals, and in severe patients than in nonsevere patients." (PMID 33774649, 2021). "In our data, Cathepsin L1 (CTSL) exhibited a 1.555-fold increase exclusively in COVID-19 lungs, which is consistent with Nie's data, but this is not shown in the human colon epithelial carcinoma cell line Caco-2 after SARS-CoV-2 infection." (PMID 34876996, 2021). "We further performed a follow-up study to determine the correlation between the CTSL level and COVID-19." (PMID 33774649, 2021). "Elevated levels of circulating CTSL in COVID-19 patients cleave the spike protein of the virus and result in increased virus entry into cells." (PMID 34445307, 2021). "In the future, experiments using live SARS-COV-2 viruses and clinical trials are needed to investigate the role of CTSL inhibitors in treating COVID-19." (PMID 33774649, 2021). "A high expression of ACE2, TMPRSS2, and cathepsin L (CTSL) in the kidneys and direct cytopathic effects of the virus are possible causes of kidney involvement during the COVID-19 pandemic." (PMID 34195193, 2021). "CTSL, which is a critical protein in the viral entry pathway for COVID-19, was upregulated in BAL of severe patients in M1 and M2 MoMa in mild patients and healthy controls." (PMID 33821282, 2021). "Cathepsin L (CTSL) is a cysteine protease recently described as involved in the establishment of COVID-19." (PMID 33918318, 2021). "IL-6 itself can increase the severity of COVID-19 by up-regulating angiotensin-converting enzyme 2 receptor and inducing cathepsin L production in macrophages, thus mediating the cleavage of the S1 subunit of the coronavirus surface spike glycoprotein." (PMID 34578898, 2021). "Additional in vitro and in vivo testing of the identified phytochemical inhibitors of TMPRSS2 and cathepsin L is needed before these molecules can enter clinical trials against COVID-19." (PMID 32842606, 2020). "This raised the question of whether elevated cathepsin L is responsible for the increased COVID-19 vulnerability in patients with diabetes." (PMID 39150053, 2024). "Teicoplanin inhibits the release of the viral genome and the viral replication cycle by cleaving the spike protein at low pH with cathepsin L, which enters the cell and targets the S protein in case of COVID-19, at the late endosomes during the early stages of viral replication." (PMID 39683724, 2024). "This indicates that circulating Cathepsin L may exacerbate viral entry during the inflammation that accompanies COVID-19." (PMID 39205219, 2024). "The expression levels of ACAT1 and CTSL show opposite trends in AD patients and COVID-19 patients." (PMID 38257800, 2024). "Whether these chronic comorbidities contribute to increased morbidity and mortality of COVID-19 by increasing CTSL activity and concentration requires further investigation in the future." (PMID 39150053, 2024). "This study identified that CTSL maturation induced by hyperglycemia may contribute to the higher mortality and severity of COVID-19 in patients with diabetes." (PMID 39150053, 2024).
COVID-19 (continued). "Measuring the impact of CTSL on the immunoglobulin levels, cytokines and B and T cells, we again observed a positive impact and dramatically increased levels of some cytokines in the subgroup with severe COVID-19." (PMID 38137381, 2023). "Interestingly, it is reported that cathepsin L protein and mRNA levels are increased in SARS-CoV-2-infected Huh-7 cells, while also, cathepsin L is significantly upregulated in both plasma levels and lungs of COVID-19 patients." (PMID 36985290, 2023). "Next, we explored how the expression of ACE2, ADAM17 and CTSL in specific cell subsets correlated with three key clinical features (age, sex, and cardiovascular comorbidities) that might make COVID-19 more severe." (PMID 37259108, 2023). "Regarding the influence of CTSL and the comparison of the mean values in the separated groups according to the severity of COVID-19 and the correlation analysis, a positive relationship between CTSL, total IgA (p = 0.005, r = 0.437) and IL-28A was established (p = 0.013, r = 0.592)." (PMID 38137381, 2023). "Glial cells express SARS-COV-2 receptors such as angiotensin converting enzyme 2 (ACE2) and cathepsin L (CTSL), which may be responsible for making glioma patients more susceptible to SARS-CoV-2 infection and at higher risk for severe COVID-19." (PMID 38053181, 2023). "Due to the importance of both ACE2 and CTSL in the context of COVID-19, it is important for those biomarkers to be studied in order to evaluate whether they have an impact on the immune response and disease severity." (PMID 38137381, 2023). "This correlates with reports showing that cathepsin L expression, but not TMPRRS2 expression, is particularly prominent in macrophages and endothelial cells, with a demonstrated correlation between circulating levels of cathepsin L and disease course and severity in patients with COVID-19." (PMID 35682644, 2022). "Lastly, our observation that CTSL, a protein crucial for COVID-19 viral entry is upregulated across multiple cell types in severe patients provides a potential initial mechanism for the induction of the NEAT1 and MALAT1 mediated inflammatory state through increased efficiency of viral entry." (PMID 35007307, 2022). "In conclusion, these data demonstrate that CTSL may play an important role in COVID-19 pathogenesis in normal and cancerous lung tissues." (PMID 35414771, 2022). "These triple target inhibitors of both SARS-CoV-2 proteases and human cathepsin L may lead to a new multi-target strategy for COVID-19 treatment." (PMID 35745663, 2022). "Moreover, targeting both transmembrane Serine Protease and cathepsin L is important to attain a synergistic effect against COVID-19." (PMID 34222852, 2021). "This showed the potential role of cathepsin L for priming of COVID-19 S protein in the lysosome." (PMID 34222852, 2021). "It indicated that CTSL could be a promising therapeutic target for the prevention and treatment of COVID-19." (PMID 33774649, 2021). "Thus, the targeting of both cell surface and cathepsin L endosomal entry pathways have been reported as potential treatment strategies for COVID-19 patients." (PMID 34356057, 2021). "As the CTSL level is significantly elevated in the plasma of patients with COVID-19, we speculated that CTSL may be an important biomarker and therapeutic target for COVID-19." (PMID 33774649, 2021). "Selective inhibitors of cathepsin L can be considered for the therapy of COVID-19." (PMID 32604797, 2020). "Additionally, therapies targeting cathepsin L could also potentially help to treat COVID-19, especially in patients with diabetes, although more research is needed to develop and test these treatments." (PMID 39150053, 2024). "To determine the effect of COVID-19 and vaccines on human health, we examined serum levels of ACE2, CTSL, AngII and TNFα in hospitalized adult patients 14 days after the onset of COVID-19 infection, healthy controls and subjects vaccinated with two doses of COVID-19 mRNA vaccines." (PMID 38137381, 2023).